DHX29 (DExH-box helicase 29)
Description:
ATP-binding RNA helicase involved in translation initiation. Part of the 43S pre-initiation complex that is required for efficient initiation on mRNAs of higher eukaryotes with structured 5'-UTRs by promoting efficient NTPase-dependent 48S complex formation. Specifically binds to the 40S ribosome near the mRNA entrance. Does not possess a processive helicase activity.
Synonyms: DDX29
Tractability: PROTAC: ubiquitination databases record sites on it; its protein half-life has been measured.
Target class: Enzyme; Hydrolase
Gene: Protein-coding gene on chromosome 5 (55,256,055 to 55,307,707, reverse strand). Ensembl gene ENSG00000067248.
Subcellular location: Cytoplasm
Subcellular location (Human Protein Atlas): Cytosol
Gene Ontology:
Molecular function: cadherin binding; ribonucleoside triphosphate phosphatase activity; ribosomal small subunit binding; RNA binding; translation activator activity; helicase activity; ATP binding; ATP hydrolysis activity; hydrolase activity, acting on acid anhydrides, in phosphorus-containing anhydrides; nucleic acid binding; RNA helicase activity
Biological process: formation of translation preinitiation complex; ribosome assembly; positive regulation of translation; positive regulation of translational initiation; translational initiation
Cellular component: cytosolic small ribosomal subunit; eukaryotic 43S preinitiation complex; cytoplasm
Genetic constraint (gnomAD): Loss-of-function variants: 53 observed, 115.29 expected, observed/expected ratio (o/e) 0.46, 90% interval 0.37 to 0.58. The upper end of that interval is the gene's LOEUF score, 0.58, which puts it in group 2 of 6, group 1 being the genes least tolerant of losing a copy. Missense variants: 1,036 observed, 1,243.2 expected, observed/expected ratio (o/e) 0.83, 90% interval 0.79 to 0.88. Synonymous variants: 416 observed, 436.53 expected, observed/expected ratio (o/e) 0.95, 90% interval 0.88 to 1.03.
Homologues: Orthologues: chimpanzee DHX29 (99% identical), macaque DHX29 (98% identical), rabbit DHX29 (95% identical), dog DHX29 (95% identical), pig DHX29 (94% identical), mouse Dhx29 (91% identical), guinea pig DHX29 (91% identical), rat Dhx29 (91% identical), tropical clawed frog dhx29 (71% identical), zebrafish dhx29 (62% identical). Paralogues in human: DHX57 (29% identical), DHX36 (26% identical), DHX9 (24% identical), YTHDC2 (24% identical), DHX30 (22% identical), DHX34 (20% identical), TDRD9 (18% identical), DHX15 (18% identical), DHX16 (18% identical), DHX8 (17% identical), DHX37 (17% identical), DHX38 (17% identical), and 6 more.
Diseases named in the same sentence as DHX29 in open-access papers:
DHX29 is named in the same sentence as 19 diseases in open-access papers, as found by Europe PMC text mining. Sharing a sentence is not in itself a finding about the gene and the disease. The quoted sentences say what the papers report.
viral infection (4 papers, 2016 to 2026). "DHX29 activates the RIG-I/MAVS-dependent signaling pathway, making it important for immune responses and potential drug/vaccine design against viral infections." (PMID 38513890, 2024). "DDX3, DHX29, DHX36, and DDX60 RNA helicases have been reported to be involved in RLR-mediated type I IFN production after viral infection." (PMID 27252702, 2016). "Thus, our systematic investigation indicates that DHX29 is ubiquitously expressed in all tissues and cell types tested from human and mice, albeit with different expression levels, suggesting that DHX29 might have cell-type specific function in response to viral infection." (PMID 29462185, 2018). "DHX29 does not interact with LGP2 or RIG-I even after viral infection, suggesting that the N-terminus of DHX29 specifically binds to the N-terminal (CARD-containing) domain of MDA5." (PMID 29462185, 2018).
glioblastoma (2 papers, 2021 to 2024). The most malignant astrocytic tumor (WHO grade IV). "However, a previous study has shown that DHX29 is overexpressed in various types of cancers, including glioblastoma multiforme, metastatic melanoma, ovarian endometrioid carcinoma and ovarian serous adenocarcinoma." (PMID 34552058, 2021).
adenoma (1 paper, 2021). A neoplasm arising from the epithelium. "As Wnt signaling is frequently over-activated in different cancers especially colorectal cancer, we examined the levels of DHX29 mRNA in early adenomas (polyps) obtained from Familial Adenomatous Polyposis (FAP) patients." (PMID 34552058, 2021). "Here we demonstrate that DHX29 mRNA levels are reduced in adenomas obtained from FAP patients." (PMID 34552058, 2021).
hepatocellular carcinoma (1 paper, 2023). A malignant tumor that arises from hepatocytes. "Previously, many studies have found that DHX9, DHX15, DDX24, DHX29, etc. are widely involved in tumor progression through various pathways, however, the role of DHX37, as an important member of the DEAD/H-box RNA helicase family, in hepatocellular carcinoma progression has been less studied." (PMID 37958405, 2023).
non-small cell lung carcinoma (1 paper, 2021). A group of at least three distinct histological types of lung cancer, including non-small cell squamous cell carcinoma, adenocarcinoma, and large cell carcinoma. "DHX29 silencing was shown to inhibit cancer cell proliferation and it is significantly overexpressed in non-small cell lung carcinoma‏ (NSCLC) malignancies." (PMID 34552058, 2021).
cancer (11 papers, 2016 to 2026). A tumor composed of atypical neoplastic, often pleomorphic cells that invade other tissues. "DHX29 encodes a protein functions in translation initiation, and knockdown of DHX29 reduces protein translation and impaired cancer cells proliferation." (PMID 34738870, 2021). "It is possible that DHX29 is involved in the translational initiation of different sets of genes in different stages of cancer development." (PMID 34552058, 2021). "Depleting DHX29 by RNAi disrupts polysomes, suppresses translation, and inhibits cancer cell proliferation." (PMID 32575790, 2020). "It is also noteworthy that the overexpression of DHX29 can promote cancer cell growth in culture and in xenografts." (PMID 32850739, 2020). "Whether DHX29 is a viable anti-cancer target whose inhibition could achieve a workable therapeutic index remains to be explored." (PMID 32575790, 2020). "However, targeting DHX29 in order to suppress cancer cell growth in a clinical setup may prove difficult due to the complexity of its function during cancer development and progression." (PMID 34552058, 2021). "Finally DHX29 is a helicase protein that participates in translation initiation, and its down-regulation has an inhibitory effect on cancer growth, which may be related to the altered cellular processes in TB." (PMID 26818387, 2016). "To demonstrate the mechanisms through which cancer cells sense cytosolic Poly(I:C) and Poly(dA:dT), we first examined the activation and expression of PKR, TLR3, RIG-I, MDA5, LGP2, and DHX29 stimulated by Poly(I:C) and Poly(dA:dT) in PANC-1 cells." (PMID 33490069, 2020). "Furthermore, the analysis of MAX, DHX29, and TAPBP mRNA in pre-treatment and on-treatment analyses of pan-cancer patients treated with anti-PD1 therapy exhibited predictive value in discriminating PFS." (PMID 38513890, 2024).
tumor (3 papers, 2012 to 2023). "Integrator complex subunit 6 (INTS6), a putative tumor suppressor shown to downregulate Wnt/β-catenin signaling was also depleted upon the elimination of DHX29 expression." (PMID 34552058, 2021). "Together, our data indicate that DHX29 may function as a new canonical Wnt signaling tumor suppressor and demonstrates that this screening approach can be used as a strategy for rapid identification of novel Wnt signaling modulators." (PMID 34552058, 2021). "The absence of breaks that attenuate translation or the higher abundance (and/or activity) of some eIFs such as eIF4F, DHX29 or eIF2B found in many tumor cell lines could explain the elevated translation rates of many mRNA orthologs in Jurkat as compared with NIH3T3 cells." (PMID 22574127, 2012). "Recent studies have reported that RNA helicases play a role in the progression of a variety of tumor types, including DHX9, DHX15, DDX24, DHX29, and DHX36." (PMID 37958405, 2023).
infection (2 papers, 2018 to 2026). The state of being infected such as from the introduction of a foreign agent such as serum, vaccine, antigenic substance or organism. "We found that depleting DHX29 from primary human fibroblasts prior to infection reduced viral mRNA and protein levels and decreased HCMV replication." (PMID 42262079, 2026). "Our results suggest that the expression level of DHX29 can specifically modulate the infection ability of EMCV." (PMID 29462185, 2018). "To further determine whether the endogenous interaction between DHX29 and MDA5 occur under physiological conditions, we treated THP-1 or mDHX29-expressing MEFs with intracellular HMW Poly(I:C) or EMCV infection." (PMID 29462185, 2018).
bacterial infection (1 paper, 2024). "Unlike DHX29 or DDX19A, which act as viral RNA sensors and activators of inflammation through the NF-κB or NLRP3 pathways, DDX5 regulates the m6A modification of TLR2/4 mRNA to suppress inflammatory responses pathway during bacterial infection." (PMID 38182816, 2024).
DHX29 also shares sentences with these, for which no sentence is quoted: bladder cancer (1 paper); colorectal cancer (1); Familial adenomatous polyposis (1); HCMV infections (1); leukemia (1); melanoma (1); metastatic melanoma (1); ovarian endometrioid carcinoma (1); ovarian serous adenocarcinoma (1); viral disease (1).